GDF15 (growth differentiation factor 15)
Diseases named in the same sentence as GDF15 in open-access papers (continued):
Sharing a sentence is not in itself a finding about the gene and the disease.
Mitochondrial myopathy (continued). "The specificity of FGF-21 (respectively, GDF-15) to detect patients with mitochondrial myopathy was 89.3% (respectively, 86.4%), and the sensitivity was 67.3% (76.0%, respectively)." (PMID 29385732, 2018). "Finally, serum levels of GDF-15 – a cytokine considered a peripheral marker of mitochondrial myopathies – were elevated in both patient groups compared to controls, without any significant difference between the two." (PMID 41357352, 2025). "Elevated circulating levels of GDF15 have been reported in patients with mitochondrial myopathies." (PMID 39976232, 2025). "Neutralizing GDF15 may be a promising therapy for enhancing muscle function and physical performance in mice with mitochondrial myopathies." (PMID 40837873, 2025). "Moreover, in mitochondrial myopathy progression, both GDF15 and FGF21 are markedly up-regulated by the integrated mitochondrial stress response (ISRmt), serving as molecular signatures of this disease." (PMID 40837873, 2025). "Besides corticosterone, other factors and pathways, such as inflammatory signalling and growth factors, likely play important roles in the pathogenesis of mitochondrial myopathy and mediate the beneficial effects of GDF15 neutralization in POLG mice." (PMID 39976232, 2025). "As both FGF21 and GDF15 are serum proteins that are commonly elevated in mitochondrial myopathies, they may serve as biomarkers of target engagement and treatment responses in IMMD therapeutic trials." (PMID 35700042, 2022). "In analogy with mitochondrial myopathies, elevated levels of GDF-15 are detected in IBM patients." (PMID 36361969, 2022). "It is currently not fully understood whether FGF-21 and GDF-15 are altered in mitochondrial diseases predominantly with specific organ involvement (e.g., mitochondrial myopathies) or more generally indicate mitochondrial dysfunction." (PMID 34572118, 2021). "GDF-15, a biomarker identified in the analysis of transcriptomic profiling of TK2 deficient human skeletal muscle, has been proven useful in the diagnosis of mitochondrial myopathies, being especially increased in patients with mitochondrial TK2 deficiency." (PMID 31060578, 2019). "Serum concentration of GDF15 is increased with ageing and in some pathological conditions, including mitochondrial myopathies, and GDF15 may reflect mitochondrial dysfunctions that accompany the ageing process." (PMID 30203052, 2018). "However, it remains unknown whether GDF15 contributes to muscle weakness, fatigue and exercise intolerance in mitochondrial myopathy and whether GDF15 blockade could be a potential therapy for PMM." (PMID 39976232, 2025). "Thus, while GDF-15 might, under certain conditions be a broader biomarker, it remains essentially a mitochondrial myopathy marker." (PMID 33501425, 2021). "Altered pyruvate and succinate indicated a metabolic response to mitochondrial dysfunction; however, lactate or mitochondrial myopathy markers FGF-21 or GDF-15 was not changed." (PMID 35250809, 2022). "Previous studies validated both FGF21 and GDF-15 as useful biomarkers in mitochondrial myopathies, even if not highly specific." (PMID 32851462, 2020). "However, elevated GDF-15 levels in blood have been found also in non-mitochondrial myopathies and, more in general, in non-mitochondrial diseases." (PMID 41357352, 2025). "However, elevated FGF21 and GDF-15 in blood have been found also in non-mitochondrial myopathies and, more in general, in non-mitochondrial diseases." (PMID 32851462, 2020).
liver fibrosis (32 papers, 2017 to 2026). "GDF15 is implicated in liver fibrosis, both positively and negatively, depending on the context and specific mechanisms involved." (PMID 40565178, 2025). "This is supported by other studies showing an association between GDF15 and an increased risk for advanced liver fibrosis." (PMID 40076667, 2025). "Growth differentiation factor (GDF-15), an inflammatory and sarcopenic biomarkers, was found to be associated with hepatitis and liver fibrosis in NAFLD." (PMID 39498408, 2024). "These genes are known to gradually increase upon NASH progression, with Gdf15 and Ccl20 encoding proinflammatory cytokines, Col1a1 and Col1a2 encoding collagen chain proteins, and Itgbl1 known for regulating liver fibrosis." (PMID 37914694, 2023). "A recent multicentre transcriptomic study demonstrated that hepatic GDF-15 expression was positively associated with NAFLD severity and GDF-15 expression was significantly higher in patients with advanced liver fibrosis." (PMID 34663793, 2021). "Receiver operating characteristic (ROC) curve analysis was also applied to assess the diagnostic performance GDF-15 (ng/L) in diagnosis of liver fibrosis." (PMID 34777864, 2021). "Receiver operating characteristic (ROC) curve analysis was applied to assess the diagnostic performance GDF-15 (ng/L) in diagnosis of liver fibrosis." (PMID 34777864, 2021). "It has been suggested that growth differentiation factor-15 (GDF-15) concentrations increase the risk of liver fibrosis." (PMID 34663793, 2021). "Considering the chronic nature of NAFLD and that GDF-15 expression is stress-inducible, it is likely that a range of factors commonly associated with T2DM and/or liver fibrosis is also associated with increasing GDF-15 concentrations." (PMID 34663793, 2021). "Elevated GDF15 levels were found to be associated with advanced liver fibrosis in chronic liver diseases." (PMID 33178828, 2020). "When compared to the WDB group, the WDO group displayed increased hepatic expression of genes linked to inflammation (Opn, Il1rn, Gdf15), hepatic fibrosis (collagen staining, Col1A1, Thbs2, Lox) reflecting disease progression." (PMID 28422962, 2017). "On the one hand, studies have not only linked elevated GDF‐15 levels to more advanced hepatic fibrosis and the presence of hepatic decompensation, but also to hepatocyte senescence, increased liver cancer risk, and decreased survival in alcohol‐related hepatitis." (PMID 41555670, 2026). "Furthermore, GDF‐15 was linked to a higher enhanced liver fibrosis (ELF) test (ρ: 0.64; p < 0.001) and higher levels of its individual components." (PMID 41555670, 2026). "Conversely, GDF15 might have a protective role in liver fibrosis, with decreased GDF15 levels causing increased fibrosis severity, while GDF15 treatment ameliorates fibrosis." (PMID 40565178, 2025). "Furthermore, our multivariate regression analysis, adjusted for BMI, body weight, and sex, confirmed that the plasma GDF15 levels were strongly associated with liver fibrosis." (PMID 40650260, 2025). "Moreover, we highlighted the association between hepatic GDF15 levels and MASH, as well as markers of liver fibrosis, suggesting a potential causative role of GDF15 in fibrosis progression, which warrants further investigation." (PMID 40650260, 2025). "Besides this moderate correlation, advanced liver fibrosis—diagnosed via NFS—was observed to be associated with considerably elevated basal GDF15 concentrations." (PMID 36430499, 2022). "We aimed to investigate (a) whether GDF-15 concentrations were associated with liver fibrosis and involved in the relationship between T2DM and liver fibrosis and (b) what factors linked with T2DM are associated with increased GDF-15 concentrations." (PMID 34663793, 2021). "Taken together, these studies suggest that increased GDF-15 concentrations may increase the risk of liver fibrosis." (PMID 34663793, 2021).
liver fibrosis (continued). "Furthermore, data from a recent large multicentre transcriptomics study identified hepatic GDF-15 expression as a key factor strongly and positively associated with liver fibrosis severity in patients with NAFLD." (PMID 34663793, 2021). "Recently, the association between GDF15 and liver fibrosis has attracted increasing attention." (PMID 33178828, 2020). "Previous studies in mouse models of liver fibrosis showed that a neutralising antibody blocking GDF‐15 reduces hepatic stellate cell activation via TGF‐β‐signalling, a key profibrogenic pathway in liver disease." (PMID 41555670, 2026). "While some studies suggest GDF15 can ameliorate liver fibrosis by modulating liver macrophages and potentially inhibiting TGF-β signaling, others indicate it can promote fibrosis progression." (PMID 40565178, 2025). "Here, a novel non-invasive fibrosis index (MSI-F) incorporating GDF15 and decorin, effectively predicted fibrotic progression, underscoring GDF15’s utility as a biomarker in liver fibrosis assessment." (PMID 40260391, 2025). "Of note, GDF15 was also reported to have immunomodulatory effects on HSCs, suggesting its potential as a therapeutic target for liver fibrosis." (PMID 40260391, 2025). "On the other hand, high serum GDF15 levels were reported to be predictors of liver fibrosis in MASLD patients." (PMID 40260391, 2025). "In vivo, injection of antibodies against GDF15 led to a reduction of fibrosis in mouse models in which liver fibrosis was induced." (PMID 41281449, 2025). "Specifically, systemic GDF15 concentrations increase with hepatic fibrosis and correlate with liver stiffness, measured by elastography." (PMID 40076667, 2025). "In contrast to these reports, a recent study with human subjects and animal models has shown that GDF15 ameliorates liver fibrosis by metabolic reprogramming of macrophages, major players of the fibrotic process." (PMID 40565178, 2025). "Specifically, GDF15 has been found to promote the activation of hepatic stellate cells, a key event in the development of liver fibrosis, by enhancing the expression of fibrotic markers and the phosphorylation of SMAD2 and SMAD3 proteins." (PMID 39697329, 2024). "In a large cohort of more than 800 patients, GDF15 was 94% sensitive and 67% specific for the detection of a significant liver fibrosis." (PMID 40809145, 2024). "Numerous previous studies have shown that GDF-15 has an important role in myocardial fibrosis, pulmonary fibrosis, hepatic fibrosis, and renal fibrosis." (PMID 38041133, 2023). "For example, GDF15 as a serum biomarker predicts liver diseases including Non-alcoholic fatty liver disease and advanced liver fibrosis in humans." (PMID 37035249, 2023). "Elevated GDF15 levels in hepatic fibrosis strongly argue for a significant role of this cytokine in the pathogenesis of the disease." (PMID 36430499, 2022). "Previous studies of liver disease reported that serum GDF15 levels increased with the progression of liver fibrosis in HC19 and NAFLD20." (PMID 35610317, 2022). "GDF-15 concentrations are a predictor of liver fibrosis and potentially involved in the association between T2DM and liver fibrosis in NAFLD." (PMID 34663793, 2021). "Further investigations are warranted to establish the causal or consequential role of GDF-15 in liver fibrosis and to further explore the potential implementation of circulating GDF-15 as a biomarker for liver fibrosis in patients with NAFLD and T2DM." (PMID 34663793, 2021). "Subgroup І patients with mild degree of liver fibrosis showed significantly higher GDF-15 levels than control group (p value = 0), suggesting the role of this marker in early detection of liver fibrosis." (PMID 34777864, 2021). "The aim of this work was to study the clinical utility of GDF-15 serum level in prediction of the degree of liver fibrosis in patients with chronic HCV infection through correlation of its levels with fibrosis degree assessed by fibro-scan." (PMID 34777864, 2021).
liver fibrosis (continued). "Our results revealed a highly significant statistical rise in GDF-15 levels among studied chronic HCV patients with liver fibrosis when compared to the control group (p < 0.01)." (PMID 34777864, 2021). "Regression modelling, receiver operator characteristic curve analysis and Sobel test statistics were used to test associations, risk predictors and the involvement of GDF-15 in the relationship between T2DM and liver fibrosis, respectively." (PMID 34663793, 2021). "The aim of this work was to investigate the clinical utility of GDF-15 serum level as a predictor of the degree of liver fibrosis in patients with chronic HCV infection and correlation of its serum level with the fibro-scan value." (PMID 34777864, 2021). "With the current study design, we are unable to address causation and we suggest that further work is required to explore the functional role of GDF-15 in the known association between T2DM and liver fibrosis in patients with NAFLD." (PMID 34663793, 2021). "GDF-15 has been put forward as a predictive biomarker of liver fibrosis and severity in patients with chronic liver disease." (PMID 34777864, 2021). "It showed that the most sensitive independent variables to predict liver fibrosis were GDF-15 (p value 0.05) and platelets (p value 0.01)." (PMID 34777864, 2021). "Recently, the role of serum GDF15 levels in predicting advanced liver fibrosis and severity of chronic liver disease in NAFLD, alcoholic liver diseases, and chronic hepatitis B and C was reported." (PMID 33178828, 2020). "By contrast, our study showed that GDF15 has anti-inflammatory and anti-fibrotic roles in CCl4-induced chronic (3 week) liver fibrosis, which is more generally used to induce liver fibrosis than a single CCl4 injection." (PMID 29222479, 2017). "Of note, the serum concentrations of PLGF, HGF and GDF15 correlated with hepatic fibrosis assessed both non-invasively by TE and semi-quantitatively by liver biopsy." (PMID 28301573, 2017). "However, another study showed increased liver fibrosis in Gdf15−/− mice that also exhibited increased hepatic TGF-β activity and phosphorylated SMAD3." (PMID 40565178, 2025). "Furthermore, the adoptive transfer of GDF15-preprogrammed macrophages to mouse models of liver fibrosis induced by CCl4 attenuated inflammation and alleviated the progression of liver fibrosis." (PMID 40565178, 2025). "Furthermore, the adoptive transfer of GDF15-preprogrammed macrophages to mouse models of liver fibrosis attenuated inflammation and alleviated fibrosis progression." (PMID 40565178, 2025). "This further reinforces the profibrotic function of GDF-15 in liver fibrosis progression." (PMID 41333917, 2025). "GDF15 levels have been positively associated with the severity of fibrosis in patients with biopsy-proven NAFLD, indicating its potential as a biomarker for the progression of liver fibrosis." (PMID 39697329, 2024). "Moreover, the predominant macrophage infiltrating phenotype was shifted from Ly6Clow to Ly6Chi, and NF-κB signaling was hyperactivated in GDF-15 KO mice, while rGDF-15 was able to alleviate hepatic fibrosis." (PMID 39000420, 2024). "As a regulator of appetite and nutritional behavior, elevated systemic GDF15 concentrations might further represent a mechanism for amelioration of hepatic fibrosis by restricted food intake and, therefore, a reduced fat load in the liver." (PMID 36430499, 2022). "Serum GDF-15 concentrations were also positively and independently associated with ELF, FIB-4 and APRI scores and, according to stepwise analysis, contributed the most towards the total variance of each liver fibrosis biomarker." (PMID 34663793, 2021). "Thus GDF-15 has been put forward as a predictive biomarker of liver fibrosis and severity in patients with chronic liver disease." (PMID 34777864, 2021). "Consequently, further work should be carried out to elucidate the functional role of GDF-15 in liver fibrosis in NAFLD." (PMID 34663793, 2021).
liver fibrosis (continued). "It is suggested that GDF-15 plays an important role in pathogenesis of liver fibrosis." (PMID 34777864, 2021). "Levels of GDF-15 were significantly higher in patients with mild degree of fibrosis (patients’ subgroup І) when compared with the controls’ group (p < 0.01) suggesting the role of this marker in early detection of liver fibrosis." (PMID 34777864, 2021). "Therefore, GDF-15 can be used as an early predictor of liver fibrosis assisting physicians initiating treatment earlier hence achieving higher survival rate." (PMID 34777864, 2021). "Additionally, we suggested that liver fibrosis can be attenuated by the anti-inflammatory action of GDF15, based on the observation that the numbers of neutrophils and activated T cells were lower in the inflamed liver of mice treated with rGDF15." (PMID 29222479, 2017). "Thus, to investigate the beneficial effect of GDF15 in liver fibrosis, mice were co-injected with CCl4 and rGDF15 for 3 weeks." (PMID 29222479, 2017). "Additionally, some evidence suggests that GDF-15 may act as a profibrotic factor in the progression of liver fibrosis." (PMID 41333917, 2025). "In conclusion, in patients with NAFLD and T2DM, GDF-15 concentrations predicted both ≥F2 and ≥F3 liver VCTE determined fibrosis, and GDF-15 concentrations may be involved in the association between T2DM and liver fibrosis in NAFLD." (PMID 34663793, 2021). "The novel findings in this study are that in patients with NAFLD, HbA1c concentrations explain a large proportion (~30%) of the variance in GDF-15 concentrations and that circulating concentration of GDF-15 may be involved in the known association between T2DM and liver fibrosis." (PMID 34663793, 2021). "Finally, recombinant GDF15 decreased the expression of pro-inflammatory cytokines and fibrotic mediators and prevented the activation of T cells in the livers of mice with CCl4-induced liver fibrosis." (PMID 29222479, 2017). "In a mouse model of liver fibrosis, activation of TGF-β signaling was shown to be the primary mechanism of the progressive effects of GDF15 in liver fibrosis." (PMID 40565178, 2025). "The post-interventional dynamics of physiologically relevant adipokines and hepatokines (ANGPTL4, CCL5, GDF15, GPNMB, IGFBP6), as well as their correlation with fat mass reduction and improvement of liver fibrosis, were analyzed." (PMID 36430499, 2022). "Of note, base-line GDF15 serum concentrations positively correlated with NFS after correction for BMI, suggesting GDF15 as a BMI-independent marker of hepatic fibrosis in obese individuals." (PMID 36430499, 2022). "Of note, baseline GDF15 serum concentrations were positively correlated with NFS and HbA1c levels after correction for BMI, suggesting GDF15 as a BMI-independent marker of hepatic fibrosis and T2D in obese individuals." (PMID 36430499, 2022). "In support of these findings, a previous study measured serum GDF-15 concentrations in patients (in an Asian population) with both T2DM and NAFLD and showed that GDF-15 concentrations were higher in those with T2DM and advanced liver fibrosis." (PMID 34663793, 2021). "Our study also utilised a relatively small cohort and further work should also be carried out in larger cohorts with access to liver biopsy data to further investigate the role of circulating GDF-15 in the relationship between T2DM and liver fibrosis." (PMID 34663793, 2021). "We showed that impaired clearance of GDF-15 in STAB-1–/–STAB-2–/– mice leads to severe glomerular fibrosis and mild perisinusoidal hepatic fibrosis." (PMID 34975851, 2021). "Thus, GDF15 may be a good indicator of the severity of the liver fibrosis." (PMID 33178828, 2020). "Cut-offs for liver fibrosis (≥F2) were PLGF = 20.20 pg/ml, GDF15 = 1582.76 pg/ml and HGF = 2598.00 pg/ml." (PMID 28301573, 2017). "Collectively, the results of the current study indicate that GDF15 represents a promising biomarker in chronic hepatic diseases and is clinically independent of hepatic fibrosis." (PMID 41432914, 2025).